INS (insulin)
Diseases named in the same sentence as INS in open-access papers (continued):
Sharing a sentence is not in itself a finding about the gene and the disease.
Obesity (continued). "It is well recognized that brain insulin has a specific role in feeding behavior and satiety and genetic variations in an obesity risk MC4R rs17782313 affect cerebrocortical insulin signaling, resulting in an impaired insulin response in the human brain, indicating a possible interaction." (PMID 35538513, 2022). "And reducing BCAAs intake promotes fat mass loss and insulin sensitivity in mice with obesity." (PMID 36219347, 2022). "In addition, treatment of this insulin resistance with recombinant D-DT improved glucose intolerance caused by obesity, suggesting that the observed low levels of D-DT in these mice are in part responsible for impaired glucose-stimulated insulin secretion." (PMID 35091838, 2022). "Skeletal muscle is a major player for insulin mediated glucose disposal; and dysregulation of skeletal muscle metabolism can strongly influence glucose homeostasis and insulin sensitivity predisposing to obesity related metabolic diseases." (PMID 36329895, 2022). "However, in a recent study, it was reported that propionate promotes the lipid accumulation in adipocytes and causes a gradual weight gain and insulin resistance in mice, while serum propionate level is highly correlated with human obesity." (PMID 35184387, 2022). "Several studies indicate that the loss of hypothalamic insulin signaling and leptin can induce changes in energy homeostasis, excessive food intake (hyperphagia), and body weight gain, leading to obesity development." (PMID 35445066, 2022). "In a similar study, injection of clodronate liposomes in mice with diet-induced obesity caused an improvement in insulin sensitivity with a marked increase in insulin-mediated suppression of hepatic glucose production during an euglycemic hyperinsulinemic clamp." (PMID 35955975, 2022). "Numerous epidemiologic studies across several decades indicate that insulin-resistant states such as diabetes and obesity are risk factors for congestive heart failure independent of common cardiovascular disease factors such as hypertension and coronary artery diseases." (PMID 37583938, 2022). "The beneficial effects of probiotics on insulin sensitivity may be due to their effects on the expression of genes associated with fat accumulation and obesity." (PMID 35685534, 2022). "In this triple-tracer PET study, we investigated whether risk factors for obesity are associated with insulin-stimulated brain glucose uptake (BGU) and central MOR and CB1R availability in a sample of healthy, non-obese young males (n = 41)." (PMID 34728775, 2022). "However, persistent activation of CDK1 during obesity causes both beneficial and pathological consequences for the pancreatic beta cell in mice, including reduction in their insulin secretory capacity that is recovered by pharmacologic inhibition with RO-3306." (PMID 35628588, 2022). "MHOs represent between 10% and 30% of people with obesity and exhibit low cardiometabolic risk (higher insulin sensitivity, normal blood pressure, lower lipid levels of triglycerides (TGs), low-density lipoproteins, and higher levels of high-density lipoproteins)." (PMID 35629923, 2022). "Combined with the data here, we have shown that insulin affects both the afferent and efferent pathways of the neural reflex, which, combined, cause airway hyperreactivity and are potentially a physiological mechanism for obesity-related asthma." (PMID 36107629, 2022). "We hypothesized that deletion of PAR2 would abolish, or attenuate, the age-associated obesity and accompanying impairment in insulin action." (PMID 36235747, 2022). "Accordingly, the aims of this study were to compare insulin sensitivity, clearance and beta-cell function between middle-aged black South African men and women who differ in obesity prevalence and to explore sex-specific associations with total and regional adiposity." (PMID 35225824, 2022).
Obesity (continued). "Pharmacological treatment is mainly focused on insulin therapy (insulin and insulin analogues); however, it also includes nutritional awareness to reduce the risk of cardiovascular disease and obesity and exercise to improve insulin sensitivity, lipid metabolism and blood pressure." (PMID 36290306, 2022). "As the n-3 PUFAs found in fish oil (FO) are anti-inflammatory and insulin-sensitizing, supplementation of women with overweight or obesity may reduce the risk of obesity and metabolic disorders in the offspring." (PMID 36118754, 2022). "HFD-induced obesity is often associated with insulin and leptin resistance." (PMID 36226318, 2022). "We utilized primary neurons to induce synaptic insulin resistance as well as a mouse model of high-risk aging that includes a high amyloid load, neuroinflammation, and diet-induced obesity to test hypotheses on underlying mechanisms." (PMID 34986876, 2022). "Pancreatic β cell dysfunction and insulin resistance in multiple organs (such as liver and muscle) could be caused by obesity." (PMID 36109703, 2022). "Increasing evidence has linked glucose, lipid homeostasis and insulin sensitivity to the gut microbiota composition, which may play an important role in the pathogenesis of metabolic diseases, such as obesity, IR." (PMID 36229811, 2022). "Taken together, the data indicate that human obesity is associated with a blunted hypothalamic serotonergic response to fasting and that FFAs and insulin might serve as important peripheral messengers to the brain to relay information on the nutritional state." (PMID 34331964, 2021). "Obesity has been associated with insulin sensitivity also in children." (PMID 35071145, 2021). "Insulin signaling alteration is a common hallmark in T2D and obesity." (PMID 34208379, 2021). "Finally, diet-induced obesity resulted in a loss of insulin-induced increases in NAc excitatory transmission and a reduction in NAc insulin receptor surface expression." (PMID 33514676, 2021). "Elevated insulin levels can be a cause and consequence of obesity and insulin resistance." (PMID 33795778, 2021). "“Regulation of lipolysis in adipocytes” (marked as “Obesity”) was closely linked to MetS since the variations of insulin resistance severity may be related to the regulation of lipolysis in adipocytes." (PMID 35003234, 2021). "During obesity, visceral adipose tissue alterations, including the development of low level inflammation, are strongly associated with deterioration of glucose homeostasis, resulting in insulin sensitivity and high glycemia." (PMID 34379673, 2021). "Moreover, insulin signaling dysfunction in obesity caused by impaired binding of insulin-like growth factor-1 (IGF-1) to insulin receptors on osteoblasts also had a negative impact on bone remodeling." (PMID 34445970, 2021). "Consistent with this, obesity and its impaired inflammatory imbalance contributed by insulin treatment may also be one of the mechanisms underlying the relationship between insulin use and COVID-19 outcomes." (PMID 34367067, 2021). "Furthermore, Bsg deficiency significantly improved hepatic insulin signaling in mice with diet-induced obesity, as evidenced by several in vivo tolerance tests and in vitro biochemical analyses." (PMID 34676828, 2021). "Furthermore, the inhibition of insulin function was mainly caused by obesity in the adipose tissue of ob/ob mice, which secreted miR-141-3p deficiency exosomes taken up by hepatocytes." (PMID 33816504, 2021). "A more detailed molecular understanding of how the accumulation of liver TG interferes with glucose regulation and insulin sensitivity and clearance could reveal potential treatment targets to address important metabolic derangements associated with obesity." (PMID 33498493, 2021).
Obesity (continued). "A strong independent association between SHBG, FAI, and cardiovascular disease risk factors (i.e. obesity, insulin, glucose, and HDL levels, DBP, inflammatory markers) has been previously reported in peri- and premenopausal women of the large SWAN (Study of Women across the Nation) study." (PMID 34089497, 2021). "Future studies could address pathways of insulin secretion, chronic systemic inflammation or the gut microbiome, all of which have been implicated as pathways to obesity and increased metabolic disease risk." (PMID 34122148, 2021). "Importantly, MSM has been found to improve insulin sensitivity and blood glucose levels in mouse models of diet-induced obesity as well as leptin receptor-deficient (db/db) mice." (PMID 34684621, 2021). "Obesity in cats may cause IR with higher circulating insulin concentrations required to achieve normoglycemia." (PMID 33461546, 2021). "Obesity is a global health issue associated with insulin resistance and altered lipid homeostasis." (PMID 33800461, 2021). "Here, we tested associations of maternal obesity (primary exposures: BMI, leptin) and metabolic parameters (secondary exposures: glucose, C-peptide, and insulin sensitivity) with total serum concentrations of fatty acids in the first trimester of human pregnancy." (PMID 34638763, 2021). "Additionally, HLD induced obesity-linked pancreatic anomaly is controlled by a G-protein coupled adenosine A2B receptor found in insulin-positive β cells of islets of Langerhans, which is also an accepted promoter of inflammation." (PMID 34026558, 2021). "Moreover, several data suggest that high insulin levels in obesity cause an inflammatory state by impairing Treg-induced suppression." (PMID 34199040, 2021). "It has been reported to regulate insulin action in neurons, and may be involved in obesity-induced memory loss." (PMID 33435277, 2021). "Although insulin can drive each of these processes, in the context of obesity-associated NAFLD, it was recently suggested that both the insulin-mediated suppression of HGP and the induction of lipogenesis are impaired, but these results remained to be confirm by others." (PMID 34685512, 2021). "Indeed, the transplantation of CRISPR-engineered UCP-1 expressing adipocytes in obese mice restores both the glucose tolerance and the insulin sensitivity, thus reverting the obesity-associated phenotype." (PMID 33572982, 2021). "SFRP5 is expressed in insulin target tissues such as subcutaneous and visceral adipose tissue, liver, skeletal muscle as well as in beta cells and has been associated with glucose metabolism, obesity, and T2D." (PMID 34184187, 2021). "In addition, a study involving a model of obesity in the mouse identified hepatic miR-29b to regulate DNMT3a and the hormone-encoding gene energy homeostasis-associated (Enho) in modulating insulin sensitivity." (PMID 34068765, 2021). "Several local and systemic effects of obesity have been reported to contribute to these associations including increased estrogen and adipokine biosynthesis, inflammatory mediators, and elevated fasting insulin and glucose levels." (PMID 33738261, 2021). "Obesity increases the risk of T2D, and this increased risk may be attributed to adipose dysfunction, leading to the release of cytokines that inhibit insulin signaling and subsequent release of NEFA and glycerol." (PMID 34553271, 2021). "Obesity-IR association has been investigated previously, some studies suggested obesity as the cause of IR since human and animal studies show that weight loss/gain correlates closely with increasing/decreasing insulin sensitivity, respectively." (PMID 34001235, 2021). "The thyroid hormone synthesis pathway plays roles in the regulation of metabolism and energy homeostasis, regulation of insulin and thermogenesis, and is also linked to stress, alongside a range of pathologies including cancer, obesity, dyslipidemia, degenerative brain disease and dementia." (PMID 33805829, 2021).
Obesity (continued). "High levels of circulating and local estrogens, altered adipokine-concentrations, disrupted insulin signaling, modifications within the microbiome, and local and systemic effects of inflammation could contribute to the obesity and cancer association." (PMID 34093831, 2021). "Also, the major obesity-associated immune cells including monocytes, macrophages, T lymphocytes, and dendritic cells in the blood, fat, and liver and the inflammatory and insulin signaling-related gene expressions in the fat and liver were evaluated." (PMID 34135978, 2021). "In children with obesity, increased levels have been described; vaspin is directly associated with body weight, triglycerides levels, insulin concentrations, IR, and high systolic and diastolic blood pressure; on the contrary, it is negatively associated with adiponectin and endothelial function." (PMID 34684432, 2021). "However, PNS-induced modulation of gut microbiota has negative effects in leptin gene-deficient mice, suggesting that PNS’ obesity improving effects are inseparable from the interaction between intestinal flora and insulin." (PMID 34512356, 2021). "Thus, our data consistently indicate that DNMT1 deficiency in brown fat promotes obesity and impairs insulin sensitivity in mice." (PMID 34824202, 2021). "Lower activity of insulin signaling proteins is typically associated with changes in IR, and our clozapine group mice, which had obesity and hyperglycemia, exhibited impaired glucose homeostasis that was induced by reduced Akt phosphorylation and GLUT4 expression." (PMID 34206460, 2021). "It has been shown that exposure to environmental pollutants can affect both the function and survival of pancreas beta-cells, insulin release, and glucose provision, and environmental chemicals have been associated with several of the mechanisms that are involved in obesity." (PMID 34886380, 2021). "Further, the recent demonstration of the ability of TAAR1 agonists to prevent binge eating allows such compounds to address both the centrally mediated over-consumption and subsequent insulin resistance and hormone imbalance aspects of obesity and associated metabolic disorders." (PMID 34943862, 2021). "Our data show that, in agreement with previous observation, alterations in FA metabolism in response to obesity surgery may be associated to several factors such as dietary changes and a modified enzymatic activity, mainly due to a different insulin response." (PMID 34959892, 2021). "Mice lacking p110β in the same neuronal population had also decreased energy expenditure (reduced thermogenesis) leading to increased susceptibility to obesity, whereas, in contrast to the p110α subunit, p110β involved changes in peripheral insulin sensitivity." (PMID 34201257, 2021). "Obesity is associated with an increased basal lipolysis, which might be caused by an impaired sensitivity of adipocytes to insulin signaling, overexpression of the leptin gene in adipocytes, and increased circulating levels of leptin." (PMID 33498674, 2021). "Similarly, TSH mutations reducing the affinity of the hormone to its receptor and causing hypothyroidism, bioinactive leptin associated with obesity, and bioinactive insulin leading to MODY diabetes have all been described." (PMID 33468709, 2021). "Furthermore, insulin also leads to the activation of leptin, an obesity related hormone, already known to associate with breast cancer progression via transcription factors including HIF1 and its crosstalk with PI3K-AKT and ERK1/2 pathways." (PMID 34225729, 2021). "It has been indicated that obesity has a high risk for insulin sensitivity, we next examined whether infusion of ADSCs has an impact on glucose homeostasis." (PMID 33957965, 2021). "FGF23 was associated with markers of obesity, MS, insulin levels, and HOMA-IR index." (PMID 34208131, 2021).
Obesity (continued). "Furthermore, insulin dysregulation accompanying obesity is linked to cognitive decline, depression, anxiety, and altered motivation that rely on NAc excitatory transmission." (PMID 33514676, 2021). "Emerging evidence suggests that metformin could contribute to improvements in obesity-associated insulin sensitivity." (PMID 34853313, 2021). "Moreover, a Finnish study—METSIM—revealed that hsCRP levels were associated with adverse changes in insulin sensitivity and obesity-related traits, as well as with total mortality." (PMID 34440486, 2021). "Furthermore, several adipose tissue-derived miRNAs were associated with adipocyte differentiation and identified with essential roles in obesity-associated inflammation, insulin resistance, and tumor microenvironment." (PMID 33801973, 2021). "In addition, obesity causes metabolic changes such as insulin resistance and high free fatty acid concentrations, leading to arterial stiffness." (PMID 34422716, 2021). "The reduction in inflammation with both of the exercise programs in our study was associated with the improvement in insulin sensitivity, which further substantiates the role of adipose tissue inflammation in driving metabolic disease progression during obesity." (PMID 34405572, 2021). "Additionally, infants born to women with reduced insulin sensitivity have increased risk of obesity and insulin resistance during childhood." (PMID 35010978, 2021). "Accordingly, insulin is a critical regulator of adipocyte biology and resistance of insulin receptors is, on the one hand, one of the important causes of obesity, and on the other hand, one of the biggest contributors to the development of obesity." (PMID 34556110, 2021). "Besides diseases such as Cushing’s syndrome and hypothyroidism, drugs such as steroids and insulin can also cause obesity." (PMID 34959957, 2021). "They state, that this effect may contribute to insulin's anti-inflammatory role in chronic inflammation associated with obesity and type 2 diabetes." (PMID 34211985, 2021). "Concurrently, with progression of compromise to glucose uptake, insulin and leptin resistance, low‐grade inflammation, modified sympathetic activity accompanied by reduced noradrenergic innervations, and thermogenesis, obesity increased the risk of these long‐lasting energy balance disorders." (PMID 33332766, 2021). "A potential explanation for the relation between obesity plus T2D and cognitive components of impulsivity could be, to some extent, the deficiencies in central insulin signaling, which are thought to impact the brain’s dopaminergic (DA) systems." (PMID 34959979, 2021). "Aberrant insulin and leptin levels have been associated with both miscarriage and preeclampsia, both of which are increased with pregravid obesity." (PMID 34195568, 2021). "Furthermore, even in youth with normoglycemia and obesity, decreased muscle, adipose and hepatic insulin sensitivity was inversely associated to FFAs and liver fat." (PMID 33320449, 2021). "Besides, based on previous studies, overweight and obesity can increase the risk of IR, compensatory insulin hypersecretion, and the destruction of pancreatic beta cells." (PMID 33985566, 2021). "Furthermore, it has been demonstrated that insulin signaling is affected by high levels of homocysteine, which is a condition associated with obesity." (PMID 33498674, 2021). "Changes in IR typically exhibit an association with lower insulin signaling protein activity, and our risperidone-treated mice with obesity and hyperglycemia exhibited impaired glucose homeostasis due to the reduction of Akt phosphorylation and GLUT4 expression." (PMID 33401717, 2021). "Taken together, functional obesity-related disturbances not only in the adipose tissue, but also in other metabolic organs, may cause disturbances in glucose metabolism, insulin signaling, and cardiometabolic disease." (PMID 34684670, 2021).